MYC (MYC proto-oncogene, bHLH transcription factor)
Diseases named in the same sentence as MYC in open-access papers (continued):
Sharing a sentence is not in itself a finding about the gene and the disease.
tumor (continued). "Using mouse models and patient data, we show that MYC signaling is associated with low tumor cell PD-L1, low overall immune cell infiltration, and low tumor cell MHC-I expression." (PMID 35760778, 2022). "Because active c-MYC can increase glutamine bioavailability and favor tumor cells, c-MYC/miR-18a-regulated cells are more susceptible to oxidative damage due to the lack of GSH synthesis from glutamine." (PMID 36483029, 2022). "This further highlights the association of MYC signaling with the tumor immunosuppressive microenvironment." (PMID 36299592, 2022). "Activation of the c-MYC oncogene is a common molecular hallmark of many cancers contributing to both tumor initiation and progression." (PMID 35422964, 2022). "One study shows that 45% of BRCA1-mutated tumours possess MYC amplification and that BRCA1 mutations are typical in TNBC." (PMID 35267409, 2022). "To address this possibility, we used DESeq2 to normalize the data and to quantify fold-change expression differences of MYC hallmark genes in each patient-matched tumor and control tissue." (PMID 36139061, 2022). "Taken together, these results indicate that the modulation of the AP-1, MYC, and NFκB signaling pathways, possibly due to differences in the local tumor microenvironment, is associated with substantial heterogeneity within the MLC population." (PMID 35803925, 2022). "MYC also has the characteristics of a proto-oncogene and is implicated in the formation of drug resistance in tumor cells." (PMID 35563017, 2022). "(iv) MXI1, a putative tumor suppressor encoding a MYC-antagonist, was strongly upregulated by DSK638 (bars 8 vs. 7)." (PMID 35149728, 2022). "In Kmt2c-mutated tumours we show enrichment of proliferative MYC gene signatures and loss of expression of the cell cycle repressor p16INK4A." (PMID 35354467, 2022). "The oncogene MYC (also known as c-MYC) is one of the most frequently activated in human cancers, and c-MYC overexpression causes tumorigenesis and maintains tumor growth." (PMID 35541906, 2022). "The top up-regulated factor in both signatures was the karyopherin subunit alpha 2 (Kpna2), a nuclear transporter involved in the nucleocytoplasmic transport pathway of several tumor-associated proteins, including MYC and E2Fs." (PMID 36269833, 2022). "We observed that anti-PD-L1 was ineffective in MYC-driven breast cancer models, even though PD-L1 was expressed on tumor-associated myeloid cells." (PMID 35760778, 2022). "Smad nuclear-interacting protein 1 (SNIP1) is a transcription repressor related to the TGF-β signaling pathway and associates with c-MYC, a key regulator of cell proliferation and tumor development." (PMID 35449131, 2022). "Selective pressure, however, enforces mechanisms such as post-translational modifications or mutations to sustain high MYC levels, which eventually results in tumor relapse." (PMID 36611833, 2022). "In tumors with highly acquired NOTCH mutations, MYC is a common target gene that drives NOTCH-dependent tumor cell growth and metabolism." (PMID 35281118, 2022). "MYC-signaling is associated with genomic instability and can mediate the immunosuppressive microenvironment and promote cell proliferation, tumor stemness." (PMID 36299592, 2022). "c-MYC inactivation leads to tumor regression associated with re-differentiation of tumor cells in transgenic mouse models, which confirmed that the block of cell differentiation was one of the activities of c-MYC." (PMID 36133825, 2022). "Our GSVA results suggested that the high-erlotinib-resistance-score group was associated with the ‘DNA repair’ and ‘MYC targets v1′ pathways related to tumor stemness." (PMID 36139554, 2022). "Confirming a link between CDK12-/- and hyper-duplicated (4/5 tumours), we identify an additional association with MYC CN gain." (PMID 36045381, 2022). "Accordingly, MYC is supposed to control the expression of M2-specific genes in macrophages, and deficiency in MYC+ macrophages inhibits tumor growth in mouse models." (PMID 35267668, 2022).
tumor (continued). "The data together suggest that the combination of BET-HDAC inhibitors synergistically inhibits MYC protein expression and proliferation associated markers, thereby blocking the tumor progression of MYC-driven MB in vivo." (PMID 36357906, 2022). "Another result associated with the increased infiltration of anti-tumor immune cells in the DFMO-treated tumor microenvironment was DFMO-associated MYC downregulation." (PMID 34947972, 2021). "For example, the CBP-deficient tumour cells depend on P300 to sustain H3K27ac not only at the homeostatic genes but also the oncogenic expression of MYC." (PMID 34298745, 2021). "MYC is a heterogeneous proto-oncogene encoding various transcription factors, leading to participation in many aspects of tumor cellular functions." (PMID 34069906, 2021). "c-MYC is a transcription regulator encoded by the protooncogene MYC and plays an important role in promoting tumorigenesis, maintaining tumor cell growth, proliferation and differentiation, angiogenesis and apoptosis." (PMID 34950208, 2021). "AK and cSCC frequently demonstrate MYC positivity by IHC, which associates with poor tumor differentiation." (PMID 34553848, 2021). "Here, a pathway is described in which the fibroblast growth factor receptor 1 (FGFR1) activated by FGF1-derived from cancer-associated fibroblasts (CAFs) is augmenting the tumor cell intrinsic MYC signal." (PMID 34637026, 2021). "MYC is known to be associated with tumor progression in different cancers, including cervical, oral, and multiple myeloma." (PMID 33958005, 2021). "The risk score was related to E2F, MYC targets and G2/M checkpoints, which were highly relative to tumor progression and metastasis, and conversely related to apoptosis and interferon-γ response pathways." (PMID 34885178, 2021). "MYC protein is frequently upregulated in ATC tumor tissues, and its high expression has been associated with poor clinical outcome." (PMID 34761120, 2021). "Elevated expression of the oncogenic transcription factor c‐MYC (hereafter referred to as MYC) is a hallmark of cancer and is largely established by the formation of numerous tumor‐specific enhancers in the gene desert surrounding MYC." (PMID 33502116, 2021). "Consistently, tumor characteristic genes set from H collection (hallmark gene sets) in MsigDB revealed that the degree of enrichment of cluster 6 in MYC targets V1/V2 was remarkably higher than that of other clusters identified as critical for Group 3 MB." (PMID 33816256, 2021). "DNA damage response deficiency and amplified oncogenic MYC signalling characterises tumours with large values of latent representation z4." (PMID 34914736, 2021). "Expression of the altered c-MYC gene is increased in tumor cells and is associated with extensive cell proliferation and contributes to tumor development." (PMID 33723286, 2021). "We identify BRAF and MYC as key mediators of KRAS-driven tumor immune suppression and show that loss of BRAF effectively blocks tumor growth in mice." (PMID 33674596, 2021). "Such an effect is also observed in tumor cells, particularly driven by oncogenic mutations and regulated by MYC levels." (PMID 34117376, 2021). "Together, our results reveal a PLK1-FBXW7-MYC signaling circuit that underlies tumor pathogenesis and provide a potential strategy for the activation of FBXW7 against c-MYC-driven MB." (PMID 33494392, 2021). "Accordingly, c-MYC gain- and loss-of-function strategies demonstrate that HTOL anti-tumor activity was, at least in part, due to c-MYC targeting." (PMID 34769070, 2021).
tumor (continued). "For instance, the simultaneous targeting of BRD4 (by BETi) and oncogenic pathways, such as WNT and MAPK, in CRC inhibits the oncogenic expression of MYC and decreases the risk of tumour resistance." (PMID 34298745, 2021). "It was further observed that complete loss of tumor-initiating capacity was capable of causing disruption in c-MYC in GBM CSCs." (PMID 34745848, 2021). "Casey found that the use of tumor cells and mice models, such as mice and human tumor cells, inhibits MYC, resulting in a loss of the PD-L1 mRNA and protein levels." (PMID 33540574, 2021). "GSEA analyses revealed the enrichment of tumor proliferation-associated signatures, such as E2F targets, MYC targets, and G2M checkpoint in IRGs low-risk subgroup." (PMID 34898475, 2021). "We found that RRM2B is highly amplified in multiple tumor types, particularly in MYC-amplified tumors, and is associated with increased RRM2B mRNA expression." (PMID 33868369, 2021). "The subsequent nuclear translocation of β-catenin activates inappropriate target genes, namely c-MYC and cyclin D, associated with tumor proliferation, migration, invasion, and metastasis." (PMID 34887764, 2021). "The inhibitor of ODC, DFMO, has been shown to impair MYC-associated tumor malignancy in various cancers." (PMID 34947972, 2021). "(D) Correlations between the expression of MYC and selected downstream targets in tumor-associated stroma based on GSE14548." (PMID 34169837, 2021). "JQ1 significantly downregulated MYC expression, causing a reduction in tumor burden and extending the overall survival in a MM mouse model." (PMID 35582389, 2021). "As far as BL is regarded, it is known that MYC oncogene, the molecular hallmark of the tumor, is responsible for profound effects on cell metabolism." (PMID 34557403, 2021). "In TNBC, miR-9 was shown to be associated with MYC amplification, tumor grade, metastatic status and poor disease-free survival." (PMID 33572395, 2021). "MYC promotes cell proliferation and restrains differentiation, and its transcription factor has been implicated in the control of several aspects of tumor cell biology." (PMID 35008789, 2021). "The association of the c-MYC gene with tumor progression can partially be explained by its role in regulating the cell cycle, as it is a regulator of the cyclin-dependent kinases." (PMID 34204834, 2021). "Our results lead us to conclude that the expression of Lef1 in Apc-deficient epithelial cells blunts tumor initiation and growth by restricting MYC activity and the number of tumor-associated ectopic crypts that provide niches for tumor stem cells." (PMID 34788095, 2021). "Schulze's study showed that high MYC Targets v1 enrichment scores were associated with high mutation load, increased infiltration of pro-and anticancerous immune cells, tumor aggressiveness, and poor prognosis of ER-positive cancer." (PMID 34567213, 2021). "The translocation of c-MYC to the IgH locus is a pathologic feature of BL, however, hardly any studies have assessed c-MYC expression from the intact c-MYC allele within the tumor cells." (PMID 34277639, 2021). "Taken together, these findings indicated that the synergistic co-overexpression of TERT, E2F1, and MYC in PCa is strongly associated with poor prognosis, tumor progression, metastasis, and patient survival." (PMID 34858826, 2021). "Several lncRNAs have been shown to be involved in regulatory loops associated with MYC gene expression in different tumor types." (PMID 34440124, 2021). "Specifically, in absence of BPTF, DNA accessibility in target genes is generally low and MYC associates with low-affinity promoters, strongly affecting cell proliferation and delaying tumor development." (PMID 33801599, 2021).
tumor (continued). "FILNC1 lncRNA expression in renal cancer cells is stimulated under conditions of ATP deficiency and leads to suppression of MYC expression and decreased tumor cell survival." (PMID 34440124, 2021). "On the other, increased expression of MYC in tumour tissue was also associated with improved survival and smaller tumour size and better survival of patients with CRC." (PMID 34198662, 2021). "In DFMO and DFMO + GW5074 treatment groups, DFMO-associated MYC downregulation was associated with the infiltration of CD8+ T lymphocytes in the tumor microenvironment." (PMID 34947972, 2021). "In cancer, the MYC transcriptional network is frequently overactivated through various mechanisms such as gene duplications, somatic mutations and chromosomal translocations, which increase MYC stability, thereby allowing tumor initiation and progression." (PMID 34761120, 2021). "In the expansion part of this study, patients with specific tumour types and tumours known to harbour either MYC oncogene amplifications or β-catenin mutations were enrolled to further explore antitumour activity." (PMID 33020594, 2021). "It has been demonstrated that c-MYC overexpression is associated with tumor progression and is preferentially expressed in metastatic melanoma." (PMID 35048028, 2021). "The tumor effect induced by its overexpression is mediated by c-MYC- and YAP/TAZ-dependent transcriptional programs associated with regenerative proliferation and cell un-differentiation in these tumor types, respectively." (PMID 34571765, 2021). "An MYC transposon and transposase were co-injected to provide a second oncogenic driver necessary for tumor formation in conjunction with the Ctnnb1 mutation." (PMID 33837189, 2021). "It follows that PVT1b inhibition resulted in an escalation of MYC expression and activity, leading to an increase in cell proliferation; indeed, loss of PVT1b in vivo promoted tumour growth." (PMID 34445233, 2021). "One T3 PCCRC detected within 24 months of a negative colonoscopy exhibited pMMRs (case 9); this was the only tumor with an MYC missense mutation." (PMID 33031197, 2020). "MYC is one of the most commonly activated oncogenes implicated in the pathogenesis of human cancers and induces tumorigenesis by evading multiple tumor-suppressing checkpoint mechanisms including proliferative arrest." (PMID 33008481, 2020). "We have previously demonstrated a strong association between HER2 over-expressing tumours and c-MYC positivity, and this was linked with a poor patient outcome." (PMID 33396670, 2020). "Abundant c-MYC expression in MM is associated with immune evasion and tumor invasiveness, thus its association with poor prognosis and survival." (PMID 32019273, 2020). "Further, the fibroblast composition was inversely associated with cancer cell composition in the bulk tumor, along with an inverse association with proliferative characteristics, such as MYC signaling and glycolysis." (PMID 32485981, 2020). "CORO2A is specifically related to several tumor-associated miRNAs (such as miRNA-493) and transcription factors (such as MYC)." (PMID 32695665, 2020). "c-MYC has been shown to be expressed in humans as a macrophage classified as M2 and plays a key role in macrophage polarization and tumor-associated macrophage function." (PMID 33193630, 2020). "In this tumor, negative modulation of the CDX2/miR-615-5p/IGF2 axis was associated with increased tumor size and weight in animal models, as well as increased expression of tumor progression markers such as Ki-67, cyclin D1, c-MYC and Bcl-2." (PMID 32605009, 2020). "MYC is a highly pleiotropic DNA-binding transcription factor, and high expression of MYC is extensively implicated in promoted tumor growth, tumorigenesis, and drug resistance in diverse human cancers." (PMID 32662828, 2020).
tumor (continued). "Cysteine cathepsins are rapidly induced and activated in response to MYC both in cancer cells and tumor-associated macrophages." (PMID 33081056, 2020). "MYC and glycolysis signaling pathway were reportedly associated with tumor progression and aggressiveness." (PMID 33180829, 2020). "(a) Schematic of the experiment to extract tumor associated macrophages from the primary tumors of MYC- (n = 5) and MYC/Twist1-HCC (n = 5)." (PMID 31933479, 2020). "A retroviral strategy which can infect only dividing cells, is however associated with a risk of tumor formation, mainly due to reactivation of the c-MYC transgene." (PMID 33198288, 2020). "Together, these data illustrate an unprecedented mechanism, whereby the tumor-promoting properties of hypusinated EIF5A are linked to its ability to regulate MYC elongation and provide a rationale for the use of DHPS/EIF5A inhibitors in CRC therapy." (PMID 33303756, 2020). "The data presented in this study agree with previous data demonstrating that 8p deletions have been linked to advanced tumor stage, MYC amplification, inversely associated with ER receptor expression, and shortened overall survival." (PMID 33176745, 2020). "Induction of MYC and Twist1 expression is associated with tumor initiation and rapid onset of macrophage infiltration in early tumors which increases during tumor progression." (PMID 31933479, 2020). "miR-561 is also downregulated in human GC cell lines and tissues, and its expression was associated with tumor-node-metastasis (pTNM) staging system and suppressed MYC expression by directly binding to its 3′-untranslated region." (PMID 32150871, 2020). "Knowing that M2 macrophage population has similarities with tumor-associated macrophages, it was also important to investigate the role of MYC in the biology of TAMs." (PMID 33081056, 2020). "Our findings show that the MYC targets v1 and v2 scores are associated with tumor aggressiveness and poor prognosis in ER-positive primary tumors, as well as in metastatic breast cancer." (PMID 33143224, 2020). "Transgenic overexpression of MYC induces tumorigenesis in mice and inactivation of MYC in MYC-driven tumors causes tumor regression in multiple tumor models, further demonstrating the key role for MYC in tumorigenesis." (PMID 33251216, 2020). "Specifically, we propose CX-5461 will have efficacy in HR-deficient HGSOC and in HGSOC tumours with elevated MYC activity such as the high-MYCN HGSOC subtype associated with poor prognosis." (PMID 32457376, 2020). "The results show that MYC was significantly associated with tumor amplification, tumor immune cells, and survival times." (PMID 33193630, 2020). "Based on these results, the expression levels of miR-24 in TILs are closely associated with the tumor-inhibiting activity, and boosting mitochondrial biogenesis and fusion promotes the response to MYC-depleted TILs in mice." (PMID 32973789, 2020). "In particular, MYC silencing was associated with reduced self-renewal and tumor-initiating capability." (PMID 32722129, 2020). "MYC is supposed to control the expression of M2-specific genes in macrophages, and deficiency in MYC-positive macrophages inhibits tumor growth in mouse models." (PMID 32523087, 2020).